CXCL5 (C-X-C motif chemokine ligand 5)
Diseases named in the same sentence as CXCL5 in open-access papers (continued):
Sharing a sentence is not in itself a finding about the gene and the disease.
tumor (continued). "Accordingly, our IHC results confirmed that this up-regulation resulted from tumor cells as we detected intense CXCL1 and CXCL5 staining signals in CRC and CRLM specimens mainly concentrated in the epithelial cells of these tissues." (PMID 18578857, 2008). "CXCR2 chemokine ligands CXCL1, CXCL5 and CXCL6 were shown to be involved in chemoattraction, inflammatory responses, tumor growth and angiogenesis." (PMID 18578857, 2008). "In contrast to CXCL6, we demonstrated CXCL1 and CXCL5 mRNA and protein expression to be significantly up-regulated in CRC and CRLM tissue specimens in relation to their matched tumor neighbor tissues." (PMID 18578857, 2008). "By upregulating CXCL5 expression, KIF4A recruits MDSCs which dampens anti-tumour immunity." (PMID 41361459, 2025). "Additionally, the deregulated expression of chemokines, such as CXCL5, in the TME contributes to tumor metastasis by inducing EMT and mediating the pro-tumor activation of neutrophils." (PMID 40387965, 2025). "Furthermore, our in vitro results are corroborated by our analysis using the Tumor Immune Estimation Resource (TIMER) 2.0 database, which shows a significant correlation between CXCL5 expression and M1 macrophage infiltration in numerous cancer types." (PMID 40050422, 2025). "Transcriptional programs centered on IL1B/CXCL5 and LGALS3/IDO1 define distinct immune phenotypes that may guide future combination strategies targeting both effector and suppressive arms of the tumor immune response." (PMID 40723289, 2025). "Notably, members of the CXC chemokine family, including CXCL1, CXCL2, CXCL3, CXCL5 and CXCL8, function through the activation of CXCR1 and CXCR2, playing a key role in promoting tumour angiogenesis." (PMID 39161078, 2025). "Across multiple preclinical tumor models, RT has been shown to increase the expression of cytokines such as IL-1β, GM-CSF (CSF2), and G-CSF (CSF3), along with chemokines including CXCL1, CXCL2, CXCL5, CCL2, and CCL5." (PMID 40805288, 2025). "Taken together, these findings suggest that LCN2 may regulate CRC metastasis by exerting bidirectional effects on both tumor cells and TME cells, and the LCN2/TGFB1/CXCL5 axis discovered in this study represents just a fraction of its complex involvement." (PMID 40313933, 2025). "We used antibodies for CXCL5 and CXCL8, the two most highly expressed in PC MET TNMplot samples, via immunofluorescence to compare expression in untreated and gemcitabine treated samples from primary tumor and liver METs to normal pancreatic tissue samples." (PMID 41228334, 2025). "The early formation of metastatic niches depends on platelets, which quickly cluster around tumor cells, producing CXCL5 and CXCL7 chemokines that attract granulocytes via CXCR2 receptors, thereby creating essential but short-lived metastatic sites shortly after tumor cell arrest." (PMID 41463352, 2025). "Among them, the chemokine family, including CC (e.g., CCL1, CCL3, CCL5, CCL7, and CCL15), CXC (e.g., CXCL1, CXCL3, CXCL5, and CXCL10), XC (e.g., XCL1 and XCL2), and CX3C (e.g., CX3CL1), plays a pivotal role in tumor development, metastasis, and chemotherapy resistance 30-33." (PMID 40740234, 2025). "Interestingly, supernatant of platelet-tumor cell coculture contained CXCL2, CXCL5, CXCL7 and activated neutrophil migration." (PMID 38786066, 2024). "We also confirmed that 4 genes (PECAM1, TIMP1, CXCL5 and PDGFB) were correlated with the expression of the VEGF family, suggesting that these genes may work together with the VEGF family to promote tumor LYM." (PMID 38638428, 2024). "At the molecular level, we demonstrated that the overexpression of GP73 in HCC cells could promote the secretion of the pro-angiogenic factors CXCL5, MCP-1, and TPO, which are directly correlated with vasculature development during tumor progression." (PMID 38939041, 2024).
tumor (continued). "Additionally, an examination of tumor tissue via qPCR analysis found that the tumors expressed high levels of chemokines such as CXCL3 and CXCL5, ligands for the CXCR2 receptor." (PMID 38339310, 2024). "Additionally, many chemokines or cytokines, such as CCL20, CXCL5, and CXCL13 (Cluster 9), had significantly different expression levels between the two populations, which indicates differences in the tumor microenvironment." (PMID 38166892, 2024). "Consequently, strategies aimed at modulating the activity of CXCL1, CXCL5, and CXCL8 hold promise as potential therapeutic interventions to impede tumor angiogenesis." (PMID 38047300, 2024). "On the contrary, CXCL5, CXCL1 and CXCL2 have a tumor-promoting effect because they recruit MDSCs, which can play an immunosuppressive role by suppressing the immune function of lymphocytes through the secretion of Arg-1 and iNOS, and CXCL1 and CXCL2 also reduce the number of CD8+ T cells." (PMID 39007138, 2024). "Tumor cells that were treated with EZH2 inhibitor alone or in combination with anti-PD1 had increased H2-K1, B2m, and Ifngr1 expression, and decreased expression of neutrophil-recruiting chemokines such as Cxcl3, Cxcl5, and Ppbp (a.k.a Cxcl7)." (PMID 38265267, 2024). "Obtained results suggest the usefulness of CXCL5 and CXCL16 in the determination of distant metastases and differentiation between TNM (Tumor-Node-Metastasis) stages, as well as the usefulness of CXCL14 and CRP combination in CRC detection (primary or recurrence)." (PMID 37848726, 2023). "CXCL10, CXCL5, MMP1, CXCL12, CXCL11, CXCL2, STAT1, IL‐6 and TLR2 were hub genes in network and may promote or inhibit the homing or of immune cells in tumours and immune cell differentiation, bring intratumoral immune heterogeneity." (PMID 36524848, 2023). "Endothelial-derived CXCL5 and its receptor CXCR2 promote the migration and intravasation of RCC toward endothelial cells suggesting that crosstalk between endothelial cells and tumor cells has a direct guiding role in driving the metastatic spread of RCC." (PMID 37015905, 2023). "In MC-38 tumor grafts, using the same experimental set-up as in RM-9, radiation increased mRNA levels of CXCL1, CXCL2, CXCL3, and CXCL5 at 24 h post-treatment and protein levels of CXCL5 at 24 h and 48 h post-treatment." (PMID 38067390, 2023). "Furthermore, CXCL5 and CXCL7 released from tumor-activated platelets were identified as essential factors for neutrophil recruitment to the pre-metastatic niche, facilitating subsequent tumor cell seeding in mouse lungs." (PMID 37566060, 2023). "CXCL10, CXCL5, MMP1, CXCL12, CXCL11, CXCL2, STAT1, IL‐6 and TLR2 were hub genes, which may drive the homing of immune cells in tumours and promote immune cell differentiation." (PMID 36524848, 2023). "The Cxcl5 shRNA-expressing mPrSC cells suppressed RM-1 growth than the scramble shRNA-expressing cells, which is expected because knocking down Cxcl5 impairs MDSC recruitment and attenuates tumor growth." (PMID 36369237, 2022). "Although other members of the CXCR2 ligand family, i.e., CXCL7 and CXCL5, have frequently been reported to promote the progression of CCA, our present results indicate that CXCL1 may exert a tumor-inhibitory effect on CCA cells." (PMID 35377900, 2022). "The tumor immune estimation resource (TIMER) platform was applied to explore the correlation between infiltration levels of immune cells and the expression of four prognosis-related genes (including NR6A1, CXCL5, TGFB1, and C3)." (PMID 36071851, 2022).
tumor (continued). "First, in vivo tests have shown that blocking CXCL5 or applying CXCR2 antagonists can slow disease progression by blocking the AKT/NF‐κB signaling pathway, thereby effectively reducing the blood supply to the tumor." (PMID 35702353, 2022). "The infiltration of CAR-T cells to the tumor site is significantly reduced when the chemokine receptor expressed by T cells is not compatible with chemokines secreted by tumor cells, as noted in the case of CXCL-1, CXCL-5, and CXCL-12." (PMID 35326556, 2022). "CXCL5, a member of the proangiogenic subgroup of the CXC family, has been found to play a key role in tumor development and metastasis by interacting with its GPCR, CXCR2, and activating both the traditional EGFR and RSK1/2/AKT/ERK pathways, leading to phosphorylation of HSP27 (Heat Shock Protein)." (PMID 36164329, 2022). "Moreover, the combination of CXCL5 and CXCR2 elevates programmed death-ligand 1 (PD-L1) expression in mouse tumor cells, depending on the activation of PI3K/AKT signaling." (PMID 35935996, 2022). "In preclinical models, however, the absence of Col 1 results in the upregulation of CXCL5 in tumour cells and the recruitment of MDSCs." (PMID 36284087, 2022). "CXCL5 expression was also stronger in HCC cell lines with high metastatic potential than that in their less aggressive counterparts, due to its ability to strongly activate the ERK1/2 and PI3K/AKT signaling pathways in tumor cells." (PMID 35702353, 2022). "CXCL8/IL8, ENA-78/CXCL5, IL6, and TERC/CCL25, both in double co-culture and triple co-culture, indicated the formation of a microenvironment with chronic inflammation characteristic of the tumor stroma and the active participation of MSCs in these processes." (PMID 36354566, 2022). "Numerous previous studies have indicated that neutrophils accumulate in the tumor microenvironment or metastatic niche to promote tumor metastasis, and that alveolar ECs are able to recruit neutrophils by secreting CXCL1, CXCL2, CXCL5 and CXCL12 after tumor-derived exosomal RNA stimulation." (PMID 36612175, 2022). "Some chemokines (CCL2, CCL5, CXCL5, CXCL8) that contribute to the development of inflammation and angiogenesis are supported by other chemokines through participation in fibrosis, HBV/HCV infections, the progression of the tumor and metastasis." (PMID 36012108, 2022). "Furthermore, various neutrophil-attracting chemokines (CXCL1, CXCL2, CXCL5, CXCL6, and CXCL8) promote the migration of neutrophils to the tumor site through CXCR1 and CXCR2 receptors." (PMID 36091114, 2022). "Inhibitors of CXCL5 or its receptor CXCR2 could be potentially applied in clinic in different mechanisms, such as regulating the tumor immune microenvironment, reducing angiogenesis and progression, improving treatment utility by combination therapy." (PMID 35150082, 2022). "Moreover, tumor-derived CCL2, CCL12, CXCL5, S100A8, and S100A9 promote the recruitment of immature myeloid cells to the tumor stroma, facilitating the enrichment of both MDSC subpopulations within the TME." (PMID 33430105, 2021). "The expression of CXCL5 correlates positively with age, but not with clinical stages and tumor infiltration." (PMID 34833360, 2021). "Additionally, the levels of tumor-promoting genes (Lrp5, MMP9, Runx2, and Snail) were increased by TGFβ and CXCL5, while they were reduced by TPM4, ANXA6, and Trail." (PMID 34230453, 2021). "Interestingly, both Mon_1 and Mon_3 also expressed the matrix metalloproteinase inhibitor TIMP1 and CXCL5 (the ligand for CXCR2) that promote recruitment of suppressive granulocytes and enhance tumor growth in mice." (PMID 34921160, 2021). "Their interaction with the BMDMs and tumor cells in the collagen-I matrix increased production of GM-CSF, G-CSF, IL-6, CCL2, CCL3, CCL4 and CCL12, and reduced production of IFN-β1, LIF, VEGF, CCL17, CXCL5 and CX3CL1." (PMID 34572807, 2021).
tumor (continued). "The CXCL5/CXCR2 axis could activate multiple downstream signaling pathways, including PI3K/AKT, ERK1/2, and STAT3 to promote tumor progression in cancers." (PMID 33458757, 2021). "In contrast, PAI-1 increased the production of CXCL5, suggesting that PAI-1 might increase the tumor infiltrating CXCR2+ myeloid-derived suppressor cells (MDSCs) and tumor-associated neutrophils (TANs), both of which are known to be immunosuppressive cells." (PMID 34912726, 2021). "As AKT and STAT3 pathways were proven to be important for PC tumorigenesis, it would be reasonable to propose that CXCL5/CXCR2 signaling might activate AKT and STAT3 signaling pathways to promote tumor progression in PC." (PMID 33458757, 2021). "Although no study was found in PDAC, CXCL5 inhibition emerged as a new strategy to attenuate tumor angiogenesis and thus slow tumor progression." (PMID 34439836, 2021). "CXCL5 and CXCL9 chemokines are essential determinants of tumor development and malignancy." (PMID 33925575, 2021). "Administration of CXCL5-neutralizing antibodies attenuated tumor growth, blood vessel outgrowth and metastasis, without affecting tumor cell proliferation." (PMID 34503058, 2021). "CAF with tumor-promoting functions secrete growth factors (HGF, IGF1, CTGF, PDGF, VEGF, LIF), cytokines (IL-1, IL-4, IL-6, IL-8, IL-10, TGF-β), and chemokines (CCL2, CCL5, CXCL5, CXCL9, CXCL10, CXCL12), WNT5α, and bone morphogenic protein 4 (BMP4), which promote tumor progression." (PMID 35008832, 2021). "Factors that can promote the anti-tumor neutrophil phenotype include chemokines (e.g., CXCL2, CXCL5, CXCL8, CCL2, CCL3, CCL5, CXCL12 (SDF-1), CXCL16 and IL-8) alone or together with G-CSF/GM-CSF, TNFα, IFNβ, IFNγ, IFNγ together with TNFα, Resolvin D1, hepatocyte growth factor (HGF) and IL-17." (PMID 34572138, 2021). "Interestingly, tumor exosomal RNAs activate alveolar epithelial toll-like receptor 3 (TLR3) to induce chemokines (CXCL1, CXCL2, CXCL5, and CXCL12) that are critical for neutrophil recruitment and lung pre-metastatic niche formation." (PMID 33101283, 2020). "This implies that the mechanism in which CAFs protect tumor cells from FSS involves forming stable cell aggregates that can persist even when subjected to FSS over 1,000 dyn/cm2 along with the secretion of soluble factors such as CCL2, CCL7 and CXCL5." (PMID 32256977, 2020). "An elevated expression of CXCL5 was observed in tumor tissues and GC cell lines compared to non-tumor tissues and normal gastric epithelial cell line, respectively." (PMID 32632106, 2020). "Expression of CXCL5, CXCL9, and CXCL10 was significantly negatively correlated with tumor purity." (PMID 33323542, 2020). "The main population of TAMs comprises CD163+ M2 macrophages, and CD163+ TAMs release soluble (s)CD163 and several proinflammatory chemokines (CXCL5, CXCL10, CCL19, etc.)as a result of TAM activation to induce an immunosuppressive tumor microenvironment together with other immunosuppressive cells." (PMID 32707850, 2020). "In combination with the anti-CXCL5 mAb, 1400 W or anti-GM-CSF mAb, anti-PD-L1mAb reduced PMN-MDSC accumulation in the primary tumours, bone marrow and the lungs more significantly than anti-PD-L1 mAb treatment alone or anti-CXCL5 mAb, 1400 W or anti-GM-CSF mAb treatment alone." (PMID 31819035, 2019). "One of the mechanisms by which this circulating neutrophilia and accumulation in tumor develops is likely related to the direct release from tumor cells of cytokines such as CXCL1, CXCL5 and, in particular, IL-8 which is known to be a potent chemoattractant for neutrophils." (PMID 31824850, 2019).
tumor (continued). "Additionally, activated platelets lead to the release of tumor growth factors and chemokines, such as platelet-derived growth factor (PDGF), vascular endothelial growth factor (VEGF) and CXCL5 and CXCL7, which stimulate cancer growth and metastasis." (PMID 30646853, 2019). "In conclusion, our study revealed that CXCL5 promotes tumor angiogenesis by controlling FOXD1 expression and transcriptional activity through the activation of the AKT/NF-κB pathway, suggesting that CXCL5 is a significant predictor in tumorigenesis and progression." (PMID 30792394, 2019). "In contrast, tumor cell induced CXCL5 and CXCL7 release from platelets was not impacted by heparin pretreatment in citrated plasma." (PMID 29346400, 2018). "Thus, the CXCL5 release seems to depend on two mechanisms taking place in parallel—a direct contact formation between platelets and MV3 tumor cells and the generation of thrombin." (PMID 29346400, 2018). "In addition, proteins involved in tumor cells invasion such as CXCL1, CXCL5, and MMP1 were displayed to be expressed and interacted with ICAM-1 and TGFβ2 in the network analysis." (PMID 29966014, 2018). "Furthermore, as the tumor cells secrete TGFβ, deletion of TGFβ receptor 2 (Tgfbr2) within the tumor is demonstrated to increase CXCL1/CXCL5 –CXCR2 chemokine and chemokine receptor signaling." (PMID 29966014, 2018). "CXCL5 is a chemokine that can recruit neutrophils and CXCR2+ myeloid cells, including myeloid-derived suppressor cells (MDSCs) and monocytes that can be a precursor of TAMs in tumor-bearing hosts." (PMID 29643991, 2018). "The CXCL1, CXCL5, and CXCL6 chemokines have the ELR motif proximal to the CXC sequence, and all ELR containing CXC chemokines have been shown to be potent promoters of tumor hemangiogenesis." (PMID 28624797, 2017). "The pro-inflammatory proteins (RANTES CXCL5, IL6) may result from the “host” response tumor cells, mainly injured endothelial cells, as reflected by the high prevalence of endothelial EVs." (PMID 28968987, 2017). "In addition to activating anti-tumor cytokines, JC-001 inhibited the expression of pro-tumor cytokines, including leptin, LIX (CXCL5) and SCF, in both the tumor microenvironment and in serum." (PMID 28399860, 2017). "Similarly, CXCL5, CXCL13, CCL1, CCL7 and CCL26 in WF collected from patients with T1–2 tumor tend to be higher than those with Tis, and the profiles of CXCL13, CCL27, MMP-1 and MMP-7 in WF from N1–3 patients tend to be higher than those with N0." (PMID 26313265, 2015). "We believe that CXCL5 and CXCL8 originated from HCC cells may be indicators of cell movement, shorter overall survival and tumour recurrence." (PMID 24268047, 2014). "Interestingly, MDSCs residing at the invasive tumor front express high levels of TGFB1, further leading to increased production of CXCL5 in TGFBR2-defcient primary breast cancer cells." (PMID 24429391, 2014). "High, unique expression of chemokines including CXCL1, CXCL5, and IL8 in this tumor may therefore have tumor cell origins." (PMID 25155515, 2014). "In addition to affecting the biology of the tumor cells themselves, activation of PPARγ also reduced production of the tumor cell-derived cytokines CXCL8, CXCL5, and CXCL1, which are critical for angiogenesis and tumor-stromal interactions." (PMID 22934105, 2012). "We examined if specific individual components of the tumour conditioned media (CCL2, CXCL1, CXCL5) could modulate dendritic cell maturation or cytokine secretion in response to LPS." (PMID 22125641, 2011). "Of the three CXCR2 ligands, CXCL5 is the most highly expressed in primary tumors and is therefore likely to be the major mediator of the preferential recruitment of PMN-MDSC to the primary tumor." (PMID 21980263, 2011). "It was inferred from microarray analyses of tumour cell-MSC co-cultures that several cytokines may be expressed in the tumour cells that act to promote these effects: CXCL1, CXCL5 and CXCL6, IL-6 and IL-8." (PMID 21902837, 2011).